CD80 (CD80 molecule)
Diseases named in the same sentence as CD80 in open-access papers (continued):
Sharing a sentence is not in itself a finding about the gene and the disease.
tumor (continued). "Significant surface expression of CD86 and CD80 and MHC-II molecules was noted in DCs 48 hours post-electroporation with tumor cell RNA in the presence of TNF-α and LPS." (PMID 18445282, 2008). "In this perspective, we have investigated the expression of the CD40, CD80, CD86, PD-1L, B7H2, OX40L and 4-1BBL costimulatory molecules in 10 human NB cell lines, as well as in primary tumour cells isolated from NB patients." (PMID 12771917, 2003). "In parallel, macrophages in tumor-affected lymph nodes showed a shift from MHC class I/IIhi to MHC I/IIlo subsets and reduced co-expression of MHC molecules with CD80 and CD86, indicating impaired antigen-presenting features." (PMID 42158858, 2026). "Notably, the release of DAMPs and cytokines further enhanced the maturation of dendritic cells, as shown by the upregulation of CD80 and CD86 expression on BMDCs exposed to tumor-conditioned media." (PMID 41484455, 2026). "The evaluation of the ratio of CD80 and CD86 may serve as a tool for future research in canine neoplasia." (PMID 40271486, 2025). "Despite M2 macrophages’ similar tumor-promoting role, Rnaseh2c-cKO did not affect M1 (CD80, CD86) or M2 (CD163, ARG1) marker expression in mouse HCC-infiltrating macrophages." (PMID 41361104, 2025). "Notably, the expression of co-stimulatory molecule CD80 by DCs, critical for generating tumor-antigen-specific CD8+ T cells, follows a circadian pattern, contributing to the time-of-day dosage-dependent tumor-killing potential." (PMID 40098968, 2025). "The soluble variant sCTLA-4, which is produced and secreted by the CTLA-4 gene via AS in tumor cells, may block CD8+ T cell activation by interfering with the CTLA-4/CD80 signaling pathway." (PMID 40032844, 2025). "Consequently, DC–T cells costimulatory signaling (CD80/CD86–CD28) is disrupted, while DCs engage in inhibitory interactions with TAMs and tumor cells." (PMID 41562080, 2025). "However, since CD80 is predominantly expressed by professional APCs and rarely by tumor cells, the interplay between the PD-1/PD-L1 and CD28/CTLA-4/CD80 pathways is likely to be more relevant in the context of T cell-APC interactions." (PMID 41425548, 2025). "Analyses of bulk RNA-seq of human ccRCC revealed that PDCD1LG2 and CD80 expression were upregulated in ccRCC tumours compared to normal kidney, as was expression of LGALS3, LGALS9, SELL and CD276." (PMID 40473819, 2025). "The presentation of tumor-specific epitopes to DCs or macrophages triggers the release of inflammatory cytokines, such as IL-1β, IL-6, IL-12, and TNF-α, and the upregulation of CD80/86, which induces the formation of specific Th-1 cells and DC maturation." (PMID 41375025, 2025). "Moreover, following treatment with the combination of SUP3 and Flt3L, CD103 + cDC1s within the tumor continued to exhibit high expression of co-stimulatory molecules, such as CD40, CD80, and CD86 expression." (PMID 41291775, 2025). "Cell–cell interaction analyses further demonstrate that T cells, macrophages, and dendritic cells communicate through regulatory axes such as PD-L1/PD-1 and CD80/CD28, while Tregs and plasmacytoid dendritic cells cooperatively contribute to tumor immune evasion." (PMID 41562080, 2025). "Similarly, B7 ligands B7-1 (CD80) and B7-2 (CD86) on tumor cells engage CTLA-4 on activated CD8+ T cells, outcompeting CD28 and thereby blocking co-stimulatory signals required for T cell activation, leading to CD8+ T cell anergy." (PMID 41268548, 2025). "Similarly, in NSCLC, CAR T-cell therapy is being developed to target tumor-specific antigens, such as GPC3, PD-L1, and CD80/CD86, aiming to bypass resistance mechanisms and improve patient outcomes." (PMID 40094890, 2025). "Treatment with tumor secretions (TC group) altered several classical macrophage receptors/factors, including CD206, CD80, and CD163, in bone marrow-derived macrophages (macrophages φ, control group), and BAM15 treatment did not reverse tumor-induced macrophage differentiation (TC-BAM15 group)." (PMID 40595481, 2025).
tumor (continued). "Furthermore, our in vitro and in vivo results demonstrated that TZ‐dSA3‐12 strongly induced the surface expression of CD80 and CD86 on DCs within the tumor microenvironment, and boosted the production of IFN‐γ and GzmB by tumor‐infiltrating CD8+ T cells." (PMID 40492586, 2025). "Extracellular ATP activates the P2X7 receptor on Mφ surface, inducing NLRP3 inflammasome-dependent IL - 1β release and upregulating the expression of MHC-II molecules and costimulatory molecules CD80/CD86, thereby promoting the cross-presentation of tumor antigens to CD4+ T cells." (PMID 41019083, 2025). "Moreover, despite growing evidence that RNA modifications shape immune cell function and tumor immune evasion, their regulatory influence on immune checkpoint molecules such as CD70, CD80, and TIGIT remains largely unexplored." (PMID 40565233, 2025). "CD80 expression on M1-like macrophages was induced by the tumor cell medium itself, regardless of treatment conditions." (PMID 40724825, 2025). "IL6 also drives tumor microenvironment immunosuppression through multiple mechanisms, including reduced expression of MHC-II, CD80/86, and IL-12 in dendritic cells, differentiation of dendritic cells to immunosuppressive M2 macrophages, and suppression of T-cell-mediated anti-tumor immunity." (PMID 41304808, 2025). "Overall, the transfer of immune stimulatory or regulatory molecules—CD80, CD86, OX40L, HLA-G, and PD-L1—via trogocytosis significantly inhibits anti-tumor immunity and contributes to the development of the immune-suppressive tumor microenvironment." (PMID 39741180, 2025). "Compared to the oe‐NC+M2pep‐Cs NPs/Plerixafor group, the mRNA levels of CD80, IL‐1β, and IL‐6 were significantly downregulated, and the mRNA levels of CD206 and IL‐10 were significantly upregulated in the tumor tissues of mice in the oe‐CXCR4+M2pep‐Cs NPs/Plerixafor group." (PMID 40536774, 2025). "Since these cells were in a different animal at the time of radiation, these data formally prove that the irradiated tumor environment rather than radiation results in CD80 expression in myeloid cells." (PMID 41417245, 2025). "We have shown that the killing phenotype relies on direct cell‐to‐cell interaction between the target tumor organoids and the immune cells and was observed despite the absence of CD80 and CD86 costimulatory molecules, which is in line with previous reports." (PMID 39535369, 2025). "TZ‐dSA3‐12‐treated E0771‐HER2 cancer cells markedly increased the surface expression of activation markers, including CD40, CD80, CD86, MHC‐I, and MHC‐II on bone marrow‐derived dendritic cells (BMDCs), suggesting that TZ‐dSA3‐12‐treated tumor cells enhance the antigen presentation capacity of DCs." (PMID 40492586, 2025). "Additionally, preS1‐pHLIP NMs treatment recruited significant numbers of CD3+CD8+ T cells, CD49B+ NK cells, F4/80+CD86+ M1‐polarized macrophages, CD80+CD86+ DC cells and CD11B+Ly6G+ neutrophils into the tumor tissue." (PMID 40091501, 2025). "For instance, a recent study indicates that a subset of neutrophils displaying antigen-presenting markers such as HLA-DR, CD80, and CD86 can transport tumor antigens into TDLNs during early stages of head and neck cancer, thereby initiating a tumor-specific immune response." (PMID 40549016, 2025). "The overexpression of CTLA-4 by iTregs, which, upon interaction with CD80/CD86 on dendritic cells, could suppress T lymphocyte activation or induce anergy in effector T cells, thereby diminishing anti-tumor immunity." (PMID 41203944, 2025).
tumor (continued). "Flow cytometry analysis revealed significant increases in CD80+CD86+ DCs, CD8+CD3+ T cells, and CD44+CD62L‐TEM cells, indicating that FABP5 inhibition effectively enhanced immune responses in the tumor microenvironment." (PMID 40956367, 2025). "In order to discern CTLA4 cytosolic or membrane localization, along with its ratio to CD28, we quantified and compared protein levels of CTLA4, CD28, and the ligand CD80 in the lymph nodes and in the TIME between the same patients representing specific tumor clusters." (PMID 40492347, 2025). "The fact that anti-CD80/86 has a benefit in combination with radiation suggests that at this stage of tumor therapy costimulation through CD28 is not as important as we would anticipate." (PMID 41417245, 2025). "Since most tumor cells do not express CD80 or CD86, effective PD-1 signalling occurs mainly at the interface between T cells and APCs." (PMID 41425548, 2025). "Total and activated (i.e., CD80+) dendritic cells were also significantly higher after RT + ICI in the contralateral tumor in the abscopal responsive 2250L compared to the non-abscopal 2336R." (PMID 41282221, 2025). "At the same time, according to the individual differences of patients (such as the expression levels of CD80, CD86 and PD-L1 on the surface of tumor cells), personalized combination treatment plans are formulated to improve the pertinence and effectiveness of treatment." (PMID 41112277, 2025). "As the tumor cells express ICAM1, CD58, and CD80, all of which could contribute to TcE-independent adhesion, we used human serum IgGs as a negative control for TcE-specific effects." (PMID 40445758, 2025). "Thus, CD80 and CD86 are critical for CD4 T cells and for radiation-mediated Treg expansion in the tumor immune environment." (PMID 41417245, 2025). "BI-5756 also directly suppresses tumor cell growth and upregulates MHC I, MHC II, and CD80 on tumor cells, which may subsequently enhance T cell-mediated anti-tumor responses in mixed lymphocyte reaction with A20 cells." (PMID 40942043, 2025). "The NP‐G/P+H‐treated tumor cells significantly enhanced the surface expression of maturation markers on DCs (CD80+CD86+) by 3.86, 3.27, and 1.17 folds compared with PBS, NP‐G/P, and HIFU‐treated tumor cells, respectively, indicating HIFU can promote tumor cell ferroptosis‐triggered DC maturation." (PMID 38342612, 2024). "Type 1-polarized macrophages (M1), identified by the expression of CD80, CD86, MHC II, iNOS, and CD68, were phagocytic and could impede tumor progression." (PMID 39434887, 2024). "The mature dendritic cells (CD11c+CD80+CD86+, DCs) in tumor tissues was firstly examined." (PMID 39494618, 2024). "Of note, a PD-L1/CD80 cis-heterodimerization has been reported on APCs, able to preserve the CD80 capacity to activate CD28, thereby supporting the sustained functionality of intra-tumor CD28+ T cells while repressing the inhibitory activity of PD-1 and CTLA-4." (PMID 39684559, 2024). "This includes whether CCH regression involves increased expression of CD80 and CD86, two well established markers of DC maturation, by tumor cells." (PMID 39619201, 2024). "For example, we observed significantly a lower percentage of I-A/I-E expressing cells, a higher frequency of CD80 expressing cells without any change in the proportion of CD86 expressing cells among Dectin-1+ myeloid cells in the spleen of B16 tumour model." (PMID 38668817, 2024). "Furthermore, MFI of CD80 and CD86, and percentage CD86+ cells were low on these cells before co-culture with transfected tumor cells confirming that at this stage cells were immature DC (iDC)." (PMID 39007281, 2024). "The levels of PD-1/CD80 were markedly enhanced on activated T-cell-derived sEVs (aT-sEV) when compared to sEVs derived from nonactivated T cells, but PD-1/CD80 was barely detected in sEVs from epithelial tumour cells (E-sEV)." (PMID 38719909, 2024).
tumor (continued). "Tumor cells were labeled with the anti-CD80 antibody in 4 cases (36%), including 1 case that lacked other myeloid-associated antigens on flow cytometric analysis." (PMID 39224452, 2024). "Thus, within the tumor, the CD80 is more likely to engage CTLA4 than CD28, thereby dampening the function of T cells at attacking the tumor." (PMID 39575257, 2024). "We also observed an increased infiltration of other cellular phenotypes such as F4/80+CD80+ M1 macrophages, CD11c+ dendritic cells, CD14+ monocytes and CD19+ B cells in the tumor of SLV group when compared with other control conditions such as no treatment (B16-OVA) and BLV groups." (PMID 38173045, 2024). "There was minimal staining of CD80 and SATB2 in the tumour compartment." (PMID 38635728, 2024). "Furthermore, cellular expression of CD80 and CD86 in each of the three layers was compared between the three tumor stages, respectively." (PMID 39619201, 2024). "The main ligands of CTLA-4 are CD80 and CD86, which are expressed on both APCs and tumor cells." (PMID 38791528, 2024). "However, analysis of the activation markers (CD64, PD-L1), co-stimulatory molecules (CD80) and antigen-presenting molecules (MHC-I and MHC-II) on myeloid cells revealed profound differences between tumor-bearing WT and Clec4a2−/− mice." (PMID 38532110, 2024). "Assuming similar roles of CD80 and CD86 in CCH, their expression patterns as observed in our study therefore seem to strengthen the hypothesis according to which CCH tumor cells gradually adopt the phenotype of mature APCs." (PMID 39619201, 2024). "The correlation of CD86 and CD80 with clinical outcome in canine histiocytic disease has not been reported so far, however the expression of their receptor CTLA-4 on tumor cells is associated with a worse prognosis in other malignant tumors in dogs." (PMID 38962703, 2024). "We show that tumor cells have an increased expression of several markers (CD47, IL7R, NKG7, CD80, CD84, CSF1R, NLRC5/CITA, CD2 and IRF3) that may be involved in regulating the level of immune infiltration and the effect on tumor immunity." (PMID 39001353, 2024). "Moreover, CD80 and CD86 expression was upregulated on Kaede-red versus Kaede-green tumour CCR7+ DCs, with expression levels on tumour Kaede-green CCR7+ DCs similar to migrated CCR7+ DCs in matched dLNs." (PMID 38267413, 2024). "For example, differential expression of CD80 and CD86 may correspond with disease progression and prognosis in tumor cells of hematogenic origin." (PMID 39619201, 2024). "CD86, but not CD80, blockade prevented the effector Treg response, enriched the tumor-draining lymph node migratory conventional DCs that were positive for PD-L1 and CD80 (PD-L1+CD80+), and promoted CTL priming." (PMID 38349740, 2024). "However, when TGF-β signaling is inhibited, the suppressed expression of MHC II, CD40, CD80, and CD86 on DCs by tumor supernatant is substantially attenuated." (PMID 38164187, 2024). "We found that the increased number of Ly6Clow macrophages in CD244fl/flLysMcre mice was accompanied by a significant upregulation of anti-tumorigenic macrophage markers and cytokines, including CD80, NOS2, IL6, and IFNB1, in CD11b+ sorted tumor-infiltrating macrophage populations." (PMID 38424542, 2024). "CTLA-4 is thought to be expressed only on T cells, CD80 and CD86 mainly localizing to cell membranes and rarely expressing in tumor interstitium, are expressed in activated B lymphocytes, activated T lymphocytes, macrophages, peripheral blood mononuclear cells, and DCs." (PMID 39120585, 2024). "Moreover, the NicheNetR analysis revealed the potential ligands expressed by C3–4 of LN tumor cells that drive exhausted signatures of CD8 TDYS in RR TFHL, including IL21, TNF, TGFB1, CD80, and CD86." (PMID 38012392, 2024).
tumor (continued). "Interestingly, we observed marked upregulation of a series of immune checkpoints (e.g., CD86, CD80, HAVCR2 and LGALS9) in most tumor infiltrating myeloid cells, and a unique pattern in TAMs (e.g., NECTIN2, TNFRSF14, CD276 and TNFRSF9)." (PMID 38414027, 2024). "Enhanced CD80 expression on TISCs might engage with inhibitory CTLA4 on T cells, resulting in immunosuppression and tumor progression." (PMID 38891044, 2024). "With a higher affinity for the ligands CD80 and CD86 on antigen-presenting cells (APCs) than the co-stimulation receptor CD28 on T cells, the interaction between CTLA4 and its ligands suppresses T-cell activity, thereby promoting tumor growth." (PMID 39198311, 2024). "In contrast, CD80/CD86-CTLA4 and HLAF-LILRB1/2 were found in both tumour subtypes." (PMID 38782901, 2024). "They raise the possibility that the CD28 ligands CD80 and/or CD86 may dictate Treg numbers after RT in the TC-1 tumor model." (PMID 38349740, 2024). "Upon CV-1 treatment, CD80 expression was significantly upregulated in DCs isolated from WT MC38 tumor-bearing mice, but not from IFNAR1 KO MC38 tumor-bearing mice." (PMID 38982116, 2024). "The interaction of CTLA-4 and B7 (CD80 or CD86) inhibits signal transmission to T cells, which plays a key role in maintaining homeostasis of immune responses as well as in inducing immune escape of tumor cells." (PMID 39354625, 2024). "Additionally, in the in vivo experiments, increases in CD68+/CD80+ and CD68+/CD86+ cells around the tumor region imply that Nb‐TriTE attracts or activates macrophages (particularly M1) or dendritic cells." (PMID 39234811, 2024). "Additionally, the tumor tissues of the 4 groups of mice were stained for markers, including DAPI, PanCK, CD8, NK1.1, CD80, and CD206, using multicolor immunofluorescence." (PMID 38704691, 2024). "Considering the cis-regulation between PD-L1 and CD80/CD86, tumor-intrinsic mechanisms might coregulate the expression of CD58, PD-L1, and CD80/CD86." (PMID 39349829, 2024). "However, after CD80 binds to CD28, the AICD of T cells can be avoided, leading to more durable anti-tumor activity of T cells." (PMID 39575257, 2024). "The results showed that the majority of the circulating PD-1+ and CD80+ sEVs in both healthy donors and cancer patients were positive for CD45, suggesting that immunocytes were the main source of PD-1/CD80+ sEVs regardless of tumour development." (PMID 38719909, 2024). "The results of flow cytometry showed that the supernatant of tumor cells stimulated by the CaO2 and CaO2‐HSA group could activate dendritic cells to the greatest extent, resulting in increased expression of CD80, CD86, and MHC II." (PMID 38973195, 2024). "Neither IFN-γ nor aT-sEVs affected the secretion of EGFR+ sEVs in tumour cells, indicating that PD-1/CD80+ sEVs possibly participated in the specific mediation of immune-related sEV secretion in tumours." (PMID 38719909, 2024). "Additionally, there was a significant increase in the proportion of CD80+ and CD86+ dendritic cells (DCs) within mouse tumor tissues after sgPik3cg-DHP/DGA-NVs treatment, indicating DC activation." (PMID 38296939, 2024). "For an anti-tumor T response to be generated, this process needs to be accompanied by signals that prevent peripheral tolerance to tumor antigens, such as high expression of major histocompatibility complex (MHC) molecules and co-stimulatory molecules (such as CD80, IL1, IFN-α)." (PMID 39091493, 2024). "In GCV control mice, PD-L1 inhibition had no impact on mRNA levels of Cd206, Cd38, Cd80 and Il-1β, highlighting the relevance of tumour biology and systemic impact of cancer on the side effects of PD-L1 inhibitors." (PMID 39834851, 2024). "The preferential induction of expression of CD80 may then lead to stronger dampening of the immuno-regulatory function of CTLA-4, then potentiating anti-tumour immune responses." (PMID 39315158, 2024).